RN7SL793P (RNA, 7SL, cytoplasmic 793, pseudogene)
Gene: Miscellaneous RNA gene on chromosome 12 (102,217,318 to 102,217,613, reverse strand). Ensembl gene ENSG00000264554.
Homologues: Orthologues: chimpanzee Metazoa_SRP (98% identical), macaque Metazoa_SRP (93% identical). Paralogues in human: RN7SL1 (81% identical), RN7SL2 (81% identical), RN7SL3 (80% identical), RN7SL14P (78% identical), RN7SL333P (78% identical), Metazoa_SRP (78% identical), RN7SL230P (78% identical), RN7SL478P (78% identical), RN7SL627P (78% identical), RN7SL678P (78% identical), RN7SL242P (78% identical), RN7SL451P (78% identical), and 702 more.